SMARCD1 (SWI/SNF related BAF chromatin remodeling complex subunit D1)
Diseases named in the same sentence as SMARCD1 in open-access papers (continued):
Sharing a sentence is not in itself a finding about the gene and the disease.
glioma (1 paper, 2021). A benign or malignant brain and spinal cord tumor that arises from glial cells (astrocytes, oligodendrocytes, ependymal cells). "Namely, 14 samples of low-grade glioma (LGG, WHO I and II) tissues, 15 samples of primary high-grade glioma (HGG, WHO III and IV) tissues, and 8 samples of secondary high-grade glioma tissues were taken to analyze the relative expression of Smarcd1." (PMID 33190170, 2021). "Taken together, these results illustrated that the expression of Smarcd1 was downregulated in glioma tissues and cell lines and potentially exerted the tumor suppressor role." (PMID 33190170, 2021). "In consideration of the existing results above, U251 cell line exhibited a more representative glioma phenotype than U87, and hereafter, we only analyze U251 cells to clarify the potential mechanism which Smarcd1 regulated." (PMID 33190170, 2021). "Therefore, it is reasonable that the crosstalk between Smarcd1 and Notch1 contributes to glioma chemoresistance potentially via the existence of GSCs, and strategies targeting pathways involving GSC to break up TMZ chemoresistance are the latest frontier of current GBM treatment." (PMID 33190170, 2021).
melanoma (1 paper, 2022). A malignant, usually aggressive tumor composed of atypical, neoplastic melanocytes. "The genes encoding these subunits are mutated at low frequency in melanoma, with SMARCD3 being slightly more frequently altered then the SMARCD1 and SMARCD2 genes." (PMID 35323214, 2022). "SMARCD1 and SMARCD2 also co-immunoprecitated with MITF in melanoma cells; however, the role these paralogues play in regulating melanoma tumorigenicity is not known." (PMID 35323214, 2022). "Because of their demonstrated interactions with MITF, it will be important to conduct more extensive functional studies of both SMARCD1 and SMARCD2 during melanocyte development and in melanoma." (PMID 35323214, 2022). "SMARCD1 and SMARCD2 both interact with MITF and may have important roles in melanocyte development and melanoma." (PMID 35323214, 2022).
mesothelioma (1 paper, 2024). A usually malignant and aggressive neoplasm of the mesothelium which is often associated with exposure to asbestos. "The BRD9/SMARCD1 axis exhibited promising discriminative performance in forecasting the prognosis of patients afflicted with liver hepatocellular carcinoma (LIHC) and mesothelioma." (PMID 38303608, 2024).
neuroblastoma (1 paper, 2020). Neuroblastoma (NB) is the most common solid, extracranial childhood tumor. "Valproic acid is known to alter the expression of SMARCA4 and SMARCD1 in neuroblastoma cells, and SMARCA genes are suggested as members of the neurogenic transcriptional network control." (PMID 33328862, 2020).
pancreatic cancer (1 paper, 2022). "It has been reported that gemcitabine sensitivity in pancreatic cancer is improved by induction of cellular senescence, and SMARCD1 has been reported to be involved in cellular senescence in hepatocytes." (PMID 35148461, 2022).
tumor (18 papers, 2015 to 2025). "In addition, related studies have reported that ARID2, SMARCC1, SMARCD1‐3 and other subunits have a low mutation probability in tumours, which is manifested as delection." (PMID 36883311, 2023). "The results suggested that downregulation of tumor suppressive miR-99b-5p mediates the upregulation of the mTOR/AR/SMARCD1 signaling axis, consequently promoting tumor aggressiveness and metabolic reprogramming in AA PCa and CRPC." (PMID 38256166, 2024). "The enrichment of nuclear mTOR, AR and SMARCD1 in MDA PCa 2b has indicated a more aggressive tumor phenotype in AA PCa vs. EA PCa (i.e., LNCaP, an androgen-dependent EA PCa with much lower nuclear mTOR, AR, and SMARCD1)." (PMID 38023145, 2023). "The results showed that knockdown of SMARCD1 significantly suppressed tumor weight and volume in vivo." (PMID 35148461, 2022). "In this study, we also demonstrated that transient induction of miR‐99a‐5p and knockdown of SMARCD1 affect cell proliferative capacity in vivo and confirmed that Ki‐67‐positive cells were reduced in those tumor fractions compared with controls." (PMID 35148461, 2022). "Overexpression of Smarcd1 inhibited tumor proliferation, migration and chemoresistance possibly via crosstalk with Notch1 pathway." (PMID 33190170, 2021). "Consistent with our data, the ratio of PTPMT1 E3 and SMARCD1 E5 exclusion was decreased in tumor samples compared to paired normal samples, while TERF1 E7 exhibited the opposite AS trend." (PMID 33992102, 2021). "Consistent with a previous analysis, a trend of an increased ratio of PTPMT1 E3 and SMARCD1 exon 5 (E5) inclusion isoforms was observed in tumor tissues compared to normal tissues (n = 6)." (PMID 33992102, 2021). "A previous study had demonstrated that Smarcd1 was involved in the regulation of tumor chemoresistance." (PMID 33190170, 2021). "Importantly, the depletion of Smarcd1 promoted cell proliferation, invasion, and chemoresistance, whereas enhanced expression of Smarcd1 inhibited tumor-malignant phenotypes." (PMID 33190170, 2021). "Examination of other members of the SWI/SNF complex and additional cellular complexes suggests that this “Goldilocks” phenotype may extend beyond SMARCD1, as tumor cells cannot tolerate significant alterations in several basic molecular functions while also retaining metastatic capacity." (PMID 38410477, 2024). "For instance, the knockdown of Smarcc1, Smarcd1, or Smarcd2 impaired the survival of mouse AML cells, confirming their tumor-maintaining role in this tumor type." (PMID 36810086, 2023). "To investigate the role of Smarcd1 in cell proliferation, we employed the CCK-8 assay to determine the tumor cell (U87 and U251) viability." (PMID 33190170, 2021). "For example, high expression of SMARCD1, SMARCA4 and ARID1A can promote tumor cell proliferation and invasion, accompanied by poor survival." (PMID 34937564, 2021). "Different groups of lentivirus-mediated Smarcd1 expression cells were treated with 200 μM TMZ for certain time points and then detect tumor apoptosis and cell viability by flow cytometry and CCK-8 assays, respectively." (PMID 33190170, 2021). "TrxG proteins SMARCD1 and SMARCE1 have been reported to promote tumor progression." (PMID 37581938, 2023). "We observed that neither OE nor KD of Smarcd1 significantly altered primary tumor growth." (PMID 38410477, 2024).
tumor (continued). "Smarcd1 is a pivotal subunit of the SWI/SNF complex, and here, we found that differential expression of Smarcd1 exerted little effects on the possible oncogene BRG1, which indicated that Smarcd1 could function as a tumor suppressor independent of other subunits in the SWI/SNF family." (PMID 33190170, 2021).
cancer (12 papers, 2014 to 2023). A tumor composed of atypical neoplastic, often pleomorphic cells that invade other tissues. "In this study, we also confirmed that knockdown of the SMARCD1 gene had a significant inhibitory effect on cancer cell proliferation, migration, and invasion, and also improved cell sensitivity to gemcitabine." (PMID 35148461, 2022). "Overexpression of miR‐99a‐5p induced cellular senescence, significantly inhibited cancer cell proliferation and restored sensitivity to gemcitabine by directly regulating SMARCD1." (PMID 35148461, 2022). "The immunohistochemical staining of the xenograft sections revealed that Smarcd1 upregulation lowered the positive rate of Ki-67, which referred to enhanced cancer cell proliferation." (PMID 33190170, 2021). "Besides, the activation of Notch1 signaling, which is induced by low expression of Smarcd1, is capable to maintain cancer cell stemness." (PMID 33190170, 2021). "Smarcd1 has been reported downregulated in several human malignant tumors." (PMID 33190170, 2021). "More importantly 9 new cancer genes were identified; seven of them (ARID1B, CASP8, MAP3K1, MAP3K13, NCOR1, SMARCD1, CDKN1B) carried truncating mutations and were characterized by biallelic inactivation, suggesting that they were potentially recessive cancer susceptibility genes." (PMID 26561834, 2015). "The prognostic genes for ACC and LIHC had a shared enrichment for SWI/SNF chromatin remodeler genes with SMARCD1 in ACC, and ARID1A and CHAF1B in LIHC, being the most significantly prognostic SWI/SNF genes (P < 0.0001) in these two cancer types." (PMID 37973839, 2023). "Specifically, ACTL6A, SMARCD1, SMARCA4 and BRD9 are among the top upregulated genes in cancers compared with the paired control samples." (PMID 34598711, 2021). "SMARCA5 and SMARCD1, two miR-100 targets belonging to the SWI/SNF protein family, have recently been shown to participate in differentiation of embryonal and cancer stem cells." (PMID 25537513, 2015).
prostate (1 paper, 2022). "Similarly to SMARCD1, we found that numerous downstream targets of SMARCD2 (e.g., PTGR1, TRMP8, PGC) and SMARCD3 (e.g., EGF, PIK3AP1, HSD3B1) were AR-driven genes that are involved in prostate tumorigenesis, progression and metastasis." (PMID 36611918, 2022).
SMARCD1 also shares sentences with these, for which no sentence is quoted: prostate carcinoma (5 papers); diabetes (2); Hepatic steatosis (2); hepatocellular carcinoma (2); metastatic tumors (2); abdominal aortic aneurysm (1); breast tumors (1); chronic obstructive pulmonary disease (1); Glucose intolerance (1); Hyperammonemia (1); Hypercholesterolemia (1); Hyperglycemia (1); Insulin resistance (1); invasive mole (1); liver cancer (1); malnutrition (1); Nicolaides-Baraitser syndrome (1); nonalcoholic fatty liver disease (1); nonalcoholic steatohepatitis (1); Respiratory Disease (1); sarcoma (1); steatosis (1); urea cycle disorder (1); uveal melanoma (1).